CHD8 (chromodomain helicase DNA binding protein 8)
Diseases named in the same sentence as CHD8 in open-access papers (continued):
Sharing a sentence is not in itself a finding about the gene and the disease.
neurodevelopmental disorder (26 papers, 2015 to 2025). A behavioral and cognitive disorder with onset during the developmental period that involves impaired or aberrant development of intellectual, motor, or social functions. "I endeavour to highlight some of the critical questions that still require careful and concerted attention over the next decade to bring us closer to the goal of understanding the salient mechanisms whereby CHD8 deficiency causes neurodevelopmental disorders." (PMID 38288845, 2024). "CHD7 and CHD8 are implicated in neurodevelopmental disorders, which are characterized by aberrant expression of hundreds, if not thousands, of genes that collectively regulate common molecular pathways." (PMID 38474321, 2024). "Our results suggest that the MAPK/ERK/ELK1 axis potentially contributes to the pathogenesis caused by CHD8 mutations in human neurodevelopmental disorders." (PMID 36575212, 2022). "Rare mutations in FMRP and CHD8 cause neurodevelopmental disorders with autistic features and regulate neurodevelopmental gene networks that have previously been linked to SCZ in genetic and proteomic studies." (PMID 36070311, 2022). "By disrupting these genomic interactions, or by secondary mechanisms, reduction in CHD8 expression directly and indirectly altered transcription of genes critical for neurodevelopment and previously implicated in neurodevelopmental disorders." (PMID 30692911, 2018). "Furthermore, well-known risk factors for neurodevelopmental disorders, Chd8 and Setd1a (ChIP-Atlas, Neural type, FE>1), were also identified in the E16-specific DHSs." (PMID 40501413, 2025). "In this context, this is also the first study to point out that neurodevelopmental disorders associated with CHD8 gene polymorphisms may occur dependently on the period of time an incubator is used." (PMID 39685474, 2024). "It is therefore unsurprising that loss-of-function variants in CHD8 have been associated with a spectrum of syndromic neurodevelopmental disorders (CHD8-NDD), displaying a wide range of clinical variability, with a yet unexplained higher penetrance in male subjects, and allelic heterogeneity." (PMID 38441608, 2024). "CHD8 encodes an ATP-dependent chromatin remodelling factor and mutations in chromatin regulatory factors are now known to be one of the most prevalent causes of neurodevelopmental disorders." (PMID 38288845, 2024). "Computational analyses of gene/mRNA regulatory interactions implicate known neurodevelopmental disorder risk genes (CHD8, TCF4, FMRP, BCL11B and TBR1) as regulators of this cascade and reveal pathways through which they may contribute to disease." (PMID 35031607, 2022). "As CHD8 haploinsufficiency may represent common features of haploinsufficiency of other general chromatin remodelers implicated in ASD, further characterization of CHD8 models and CHD8 genomic interactions could reveal essential functions driving pathology in neurodevelopmental disorders." (PMID 30692911, 2018). "Pathogenic variants in the CHD8 gene alone have been found in patients with ASD, and pathogenic variants in SUPT16H alone cause a variable-expressed neurodevelopmental disorder." (PMID 40984926, 2025). "Variants in ASD-associated genes (CHD8, FOXP1, and SHANK1) and genes linked to other neurodevelopmental disorders (CDH15, GATAD2B, and SHROOM4) were also detected." (PMID 40642607, 2025). "Our findings place CTNND2 alongside other WNT-regulating genes such as APC, CHD8, and CTNNB1, whose disruption similarly causes variable neurodevelopmental disorders." (PMID 41502569, 2025). "Heterozygous loss-of-function variants in CHD8 have been associated with a syndromic neurodevelopmental-disease spectrum, collectively referred to as CHD8-related neurodevelopmental disorders." (PMID 38441608, 2024).
neurodevelopmental disorder (continued). "Mutations in several genes coding for chromatin remodelers and epigenetic modulators have been linked to neurodevelopmental disorders including ASD, with causative mutations identified in several chromatin remodelers (e.g. CHD8 and ARID1B)." (PMID 33350388, 2020). "Our analysis revealed several key DEGs, which were further subjected to GO enrichment and KEGG pathway analyses.Compared to previous studies that have broadly investigated CHD8 or Notch signaling in neurodevelopmental disorders, our work presents several key innovations." (PMID 40526590, 2025). "Recently, genes involved in HSCR and ENS development (such as CHD8 and NLGN3) were also found to be implicated in neurodevelopmental disorders indicating that genetic neurodevelopmental processes might be conserved between the CNS and ENS." (PMID 33151932, 2020). "While individual studies of the role of CHD8 haploinsufficiency in neurodevelopmental disorders all highlight strong enrichment of ASD-relevant genes among DEGs, our data suggests that this signal can be separated into direct genomic interaction targets and more brain- and neuron-specific genes." (PMID 30692911, 2018). "Nevertheless, our findings strongly support a major role of CHD8 on Wnt/β-catenin signaling, and a connection between CHD8 and TCF4, and several other genes that have been implicated in neuropsychiatric and neurodevelopmental disorders, in particular, members of the DLX gene family." (PMID 28321286, 2017). "Similarly, the role of CHD8 on neuropsychiatric and neurodevelopmental disorders is multifactorial, with both direct effects on downstream targets, such as β-catenin, and indirect effects mediated by dysregulated expression of other transcription factors and chromatin remodelers." (PMID 28321286, 2017). "An ultrarare neurodevelopmental disorder, 14q11.2 microduplication syndrome involves the SUPT16H and CHD8 genes." (PMID 40984926, 2025). "Mutation of CHD8 had not been previously implicated with ASD, except in one concurrent study examining balanced chromosomal abnormalities in ASD and other neurodevelopmental disorders." (PMID 26733790, 2015).
tumor (12 papers, 2014 to 2025). "We show that CHD8 also plays a key role in TNBC pathogenesis, with detailed multi-omics analysis revealing that BCL11A and CHD8 co-regulate several targets and synergise to drive tumour development and progression." (PMID 40328966, 2025). "Chromatin remodeler CHD8 is a tumour-specific, targetable protein–protein interaction of the oncogenic transcription factor BCL11A in TNBC." (PMID 40328966, 2025). "This showed that knockdown of Chd8 using either method reduces the ability of these cells to form tumours both in vitro (3D colony formation assays) and in vivo (Xenograft tumours)." (PMID 40328966, 2025). "This view is aligned with another recent report describing an inhibitory function of kismet, the fly analog of CHD8, in intestinal stem cell proliferation, and an increasing number of studies implicating CHD8 as a tumor suppressor." (PMID 36222238, 2022). "It is intriguing that CHD8 appears to act in a pro-proliferative or pro-survival manner in most contexts but as a tumor suppressor in other malignancies, perhaps through inhibition of Wnt signaling." (PMID 26588464, 2015). "Further investigation is needed to determine the context in which CHD8 inhibition would be detrimental to the tumor and thus advantageous to patients." (PMID 26588464, 2015). "We have previously shown that CHD8 depletion in asynchronous cultures provokes a growth defect and a small G1 arrest in the C33A tumour cell line." (PMID 24265227, 2014). "Similarly, Bcl11a and Chd8 protein levels were also elevated in tumours derived from the mouse TNBC model (Brca1f/fp53+/-Blg-Cre)." (PMID 40328966, 2025). "We predicted that CHD8 depletion in transplanted B-ALL cells would increase time to disease due to attenuation of cell viability and tumor growth." (PMID 26588464, 2015).
psychiatric disorder (4 papers, 2015 to 2023). A disorder characterized by behavioral and/or psychological abnormalities, often accompanied by physical symptoms. "The recent discovery of genetic associations between several ChRFs (e.g., BAF complex, CHD8) and intellectual and psychiatric disorders, however, underscores the importance of understanding their specific roles in the CNS." (PMID 26635563, 2015). "All of the social behavioral impairments observed in female Chd8+/∆SL mice using multiple paradigms suggests the presence of psychiatric traits in patients with ASD because the multiple tasks applied to Chd8+/∆SL mice are well-established methods for animal models of human psychiatric disorders." (PMID 33933000, 2021).
infection (2 papers, 2021 to 2023). The state of being infected such as from the introduction of a foreign agent such as serum, vaccine, antigenic substance or organism. "Taken together, we propose a model in which the reduced expression of chd8 induces the breakdown of the mucosal barrier, which, in turn, drives intestinal vulnerability to infection." (PMID 36375841, 2023). "We confirmed the reduction of Chd8 and Tsc2 expression by quantitative RT-PCR after 7 days of infection." (PMID 34497307, 2021).
movement disorder (2 papers, 2022 to 2024). Neurological conditions resulting in abnormal voluntary or involuntary movement, which may impact the speed, fluency, quality and ease of movement. "The interactome of ASD with CHD8 was related to familial encephalopathy and movement disorder which conditions found in ASD individuals." (PMID 35978033, 2022).
neurological diseases (2 papers, 2020 to 2022). "We next compared our genes to gene sets of ASD or other neurological disorders and found that CHD8, DYRK1A, GRIN2B, MBD5 and SCN2A overlapped with the ASD gene sets (FDR ≤ 0.1) reported in previous large-scale ASD studies." (PMID 32193494, 2020).
cardiac diseases (1 paper, 2020). "Our study unveiled for the first time that CHD8 plays an important role in cardiomyocyte apoptosis, which also indicates its significant function in cardiac diseases." (PMID 32123560, 2020).
cardiovascular diseases (1 paper, 2020). "Our findings indicated that the mechanism underlying miR-141-3p and CHD8 interaction in H/R induced cardiomyocyte apoptosis may provide a novel therapeutic strategy against myocardial I/R injury-induced cardiovascular diseases." (PMID 32123560, 2020).
CHD8 also shares sentences with these, for which no sentence is quoted: epilepsy (6 papers); gastric cancer (4); Angelman syndrome (2); Down syndrome (2); glioblastoma (2); Huntington disease (2); language delay (2); mucosal (2); neuroblastoma (2); Obesity (2); Pitt-Hopkins syndrome (2); amyotrophic lateral sclerosis (1); anemia (1); attention deficit-hyperactivity disorder (1); Autoimmunity (1); B-cell lymphomas (1); bacterial infection (1); behavioral disorders (1); bladder cancer (1); brain disorder (1); breast tumours (1); cognitive disorder (1); Cornelia de Lange syndrome (1); endometrial cancer (1); esophageal adenocarcinoma (1); gastric tumors (1); Greig cephalopolysyndactyly syndrome (1); immune disorders (1); Impaired glucose tolerance (1); language disorder (1).
A further 14 diseases each share a sentence with CHD8 in 1 paper.